HTT (huntingtin)
Diseases named in the same sentence as HTT in open-access papers (continued):
Sharing a sentence is not in itself a finding about the gene and the disease.
Huntington disease (continued). "We propose that altered kinase signalling is a phenotype of Huntington’s disease that occurs prior to cell death; specifically, that altered kinase signalling may influence huntingtin localisation, which in turn may impact upon nuclear processes such as transcriptional regulation." (PMID 26660732, 2015). "Huntington disease (HD) is a hereditary dominant neurodegenerative disorder evoked by the excessive expansion of the CAG repeats in the HTT gene." (PMID 26092128, 2015). "However, in view of the multitude of fragments that must form the smear of immunoreactive huntingtin observed in knockin mice and in Huntington disease brain, it seems more likely that these fragments stem from the action of multiple proteolytic activities with little specificity." (PMID 24961702, 2014). "Huntington disease (HD) is an autosomal-dominantly inherited, neurodegenerative disorder caused by the abnormal expansion of a CAG repeat tract in the huntingtin gene." (PMID 24383721, 2014). "Of these protein aggregation-associated neurodegenerative diseases, Huntington's disease is caused by the expansion of CAG trinucleotide repeats in the huntingtin gene, which results in an expansion of the length of polyglutamine residues at the N-terminus of the huntingtin protein." (PMID 25101108, 2014). "Huntington disease (HD), an autosomal dominant adult-onset neurodegenerative disease caused by the abnormal expansion of the CAG-repeat tract in the huntingtin gene, represents an area of research where these new developments are of particular interest." (PMID 25144457, 2014). "Research in Huntington's disease (HD), a neurodegenerative diseases caused by trinucleotide repeat expansion in the gene (HTT) coding for the huntingtin protein, revealed that mutant huntingtin directly interacts with HAT proteins, leading to altered histone acetylation." (PMID 25071843, 2014). "This is quite unlike the situation in Huntington’s disease, which can be traced to a single genetic defect (i.e., mutations in the Huntingtin gene) or familial Alzheimer’s disease where the majority of the disease-linked genes are clustered around the amyloid precursor protein processing pathway." (PMID 23580245, 2013). "Indeed, Humbert (2010) has recently suggested that Huntington's disease, like schizophrenia, may have a neurodevelopmental aetiology, with HTT acting as a scaffold protein for many developmental processes critical for correct brain function." (PMID 21298101, 2011). "Huntington disease (HD) is an autosomal dominantly transmitted, progressive neurodegenerative disease associated with a polymorphic CAG trinucleotide repeat in the 5' part of the HTT (HD) gene, which is expanded and translated into an elongated polyglutamine tract in the huntingtin protein." (PMID 21595933, 2011). "Indeed, protein aggregates presents one of the common features in a myriad of neurodegenerative diseases, including the β-amyloid plagues in Alzheimer's disease, mutant huntingtin cytoplasmic inclusions in Huntington's disease, and the alpha-synuclein containing Lewy bodies in PD." (PMID 19754977, 2009). "Huntington disease (HD) is an inherited, incurable, autosomal dominant disease caused by the expansion of CAG trinucleotide repeats in the first exon of the huntingtin gene." (PMID 18939977, 2008). "In a cell model related to Huntington’s disease, treatment with ATT reinforced the degradation of the mutant huntingtin proteins by increasing cathepsin D maturation and autophagy flux." (PMID 40427621, 2025). "Although there is no direct evidence for SCA1, activation of glucocorticoid receptors seems to attenuate the aggregation of polyQ-expanded ataxin-3 and huntingtin proteins in SCA3 and Huntington’s disease (HD), respectively." (PMID 40029919, 2025). "Factors that enhance the production of effective nanocarriers for anti-HTT siRNA were identified and tested in a YAC128 mouse model of Huntington’s disease (HD)." (PMID 41012513, 2025).
Huntington disease (continued). "Human and mouse genetic studies have demonstrated a role for DNA mismatch repair (MMR) molecular machines in modulating the rate of somatic expansion of the huntingtin (HTT) CAG repeats, and onset and progression of Huntington's Disease (HD)." (PMID 40613711, 2025). "Huntington’s disease (HD), a fatal neurodegenerative disease, arises due to a CAG repeat expansion in the huntingtin (HTT) gene." (PMID 40748251, 2025). "Huntington's disease (HD) is a monogenic disorder characterised by a variable CAG expansion in exon 1 of the HTT gene, resulting in the expressed huntingtin protein (htt) containing an extended polyglutamine tract." (PMID 40542543, 2025). "Huntington’s disease has its own distinctive molecular feature: an expansion of CAG repeats in the HTT gene, leading to an extended polyglutamine tract in the huntingtin protein." (PMID 39684324, 2024). "Huntington’s disease (HD) arises from the expansion of CAG repeats in the Huntingtin gene, leading to the aggregation of mutant Huntingtin protein and neuronal death." (PMID 39329952, 2024). "Huntington’s disease is an ND induced by expanded cytosine, adenine, and guanine (CAG) repeats in the huntingtin gene." (PMID 36237157, 2024). "Huntington’s disease (HD) is a rare, dominantly inherited NDD resulting from a trinucleotide repeat expansion in the huntingtin (HTT) gene, presenting in midlife with a triad of psychological, physical, and cognitive impairments." (PMID 39452073, 2024). "Huntington disease (HD), a congenital progressive neurodegenerative disease, is attributed to an expanded CAG repeat in the N-terminal region of the Huntingtin gene (HTT)." (PMID 38534313, 2024). "Cumulative data from both human and animal studies underscore the intricate impact of the aberrant form of huntingtin on the HPA axis and adrenal glands in the context of Huntington’s disease pathology." (PMID 38396853, 2024). "Understanding the normal function of the Huntingtin (HTT) protein is of significance in the design and implementation of therapeutic strategies for Huntington’s disease (HD)." (PMID 39074279, 2024). "In Huntington’s disease (HD), MSD has been utilized to quantify huntingtin (HTT) protein levels, helping to track disease progression and evaluate therapeutic interventions." (PMID 39727843, 2024). "In Huntington’s disease (HD), an expansion of a CAG repeat within exon 1 of the huntingtin (HTT) gene, which produces a huntingtin (HTT) protein with an expanded polyglutamine (polyQ) repeat, leads to a progressive and fatal neurodegenerative pathology." (PMID 37553253, 2023). "Huntington's disease (HD) is a progressive neurodegenerative disorder attributed to CAG repeat expansion, which confers Mutant HTT (mHTT) toxic functions that interfere with immune and mitochondrial function, and is aberrantly modified post-translationally." (PMID 37752518, 2023). "In Huntington’s disease (HD, OMIM #143100), a late-onset monogenic dominant disorder, aggregates of mutant huntingtin (Htt) protein are present both in the cytosol and the nucleus." (PMID 38081944, 2023). "Here, we report that, in two Huntington’s disease mouse models (YAC128 and BACHD-97Q-ΔN17), mutant HTT mRNA is retained in the nucleus." (PMID 36458209, 2022). "Huntington’s disease manifests due to abnormal CAG trinucleotide expansion, in the first exon of the Huntingtin gene and disease progression involves genetic, immune, and environmental components." (PMID 36224586, 2022). "In Huntington’s disease, a CAG repeat expansion in exon 1 of the HTT gene results in the production of mutant huntingtin (mHTT) with an expanded polyglutamine stretch." (PMID 35813946, 2022). "A mutation of autosomal dominant nature on chromosome 4 with cytosine, adenine, and guanine (CAG) trinucleotide chain repeats in the Huntingtin (HTT) gene, resulting in Huntington's disease." (PMID 36381805, 2022).
Huntington disease (continued). "An inherited neurological disorder called Huntington’s disease (HD) is brought on by the HTT gene’s exon 1 developing more than 35 CAG repeats, and the resulting mutant huntingtin (mHtt) accumulates in nerve cells." (PMID 36142231, 2022). "Huntington disease (HD) is an autosomal fatal neurodegenerative disorder which manifests in progressive chorea, motor disfunction and dementia caused by the CAG expansion repeat of the huntingtin gene (HTT)." (PMID 36213737, 2022). "For example, in Huntington’s disease, expansion of the N-terminal CAG repeats fabricates a long hydrophilic poly-Q stretch on the Huntingtin protein, which favors aggregation through intramolecular hydrogen bonding and electrostatic interactions." (PMID 35269436, 2022). "In Huntington’s disease, infusion of engineered AAV5-microRNA (miHTT) into the patient’s striatum so that it binds to HTT mRNA preventing its translation into toxic HTT protein." (PMID 36430666, 2022). "For example, accumulation of β-amyloid (Aβ), α-synuclein (α-syn), and huntingtin (HTT) are found in Alzheimer’s disease (AD), Parkinson’s disease (PD), and Huntington’s disease (HD), respectively." (PMID 35499073, 2022). "Similarly, other proteins containing polyglutamine tracts, such as huntingtin and the androgen receptor, have also been found to aggregate when the polyglutamine tract is expanded, resulting in neurodegenerative diseases, such as Huntington's disease and Kennedy's disease, respectively." (PMID 34473252, 2021). "The knockdown of PFDN2 in undifferentiated neuronal cells increased the formation of aggregates of polyQ stretches and polyQ-expanded huntingtin (HTT), gene defects that are related to the neurodegenerative Huntington’s disease." (PMID 35111762, 2021). "It is interesting to mention that in another neurodegenerative disorder, such as Huntington disease, it has been demonstrated that in NG108 cells overexpressing mutant Huntingtin (mHtt) Sp1 up-regulates REST by binding its promoter sequence." (PMID 34899171, 2021). "The current example of this approach is in Huntington disease, where a CAG nucleotide repeat expansion in the huntingtin gene results in the production and accumulation of mutant protein." (PMID 32087199, 2020). "In view of huntingtin and mTRAPP-II binding to different domains in kalirin, we suggest that mTRAPP-II is the GEF compromised in Huntington’s disease." (PMID 32375403, 2020). "In Huntington’s disease, structural and functional cerebral vascular abnormalities have been shown and aggregation of mutant Huntingtin is present in the neurovascular unit, which may affect the ability of the vascular system to respond to the demands of acute exercise." (PMID 32566927, 2020). "The methodology applied here might also be useful in the analysis of human proteins with N/Q biases, such as those linked to amytrophic lateral sclerosis or huntingtin from Huntington’s disease, or to other non-N/Q-biased prion-forming domains, such as in alpha-synuclein." (PMID 32844065, 2020). "In a mouse model of Huntington’s disease (HD), IN PACAP was able to promote expression of hippocampal BDNF and decrease the formation of mutant huntingtin aggregates." (PMID 33233734, 2020). "In Huntington’s disease (HD), expression of many alternative 3′ UTR isoforms, among others the huntingtin (HTT) gene, are altered." (PMID 32408514, 2020). "Secondly, R6/2 transgenic mice possess a genomic fragment containing exon 1 of the human Huntingtin gene, which carries 144 CAG repeats, and are the most widely used model of Huntington’s disease." (PMID 31208099, 2019).
Huntington disease (continued). "For example, Huntingtin (HTT; Huntington's Disease), Frataxin (FXN; Friedreich Ataxia), and Ataxin 1/2 (ATXN1/ATXN2; Spinocerebellar Ataxias) all have GC-rich trinucleotide expansion tracks that form R-loops in vitro and associate with disease progression." (PMID 31225499, 2019). "Discovering mechanisms to reduce the cellular levels of mutant huntingtin and REST provide promising strategies for treating Huntington disease." (PMID 31361762, 2019). "While already shown to be protective against Huntington’s disease in mice, we show that increased SIRT1 expression is able to protect against mut-huntingtin toxicity in the same deacetylase-independent manner in cultured neurons." (PMID 30973934, 2019). "In Huntington’s disease (HD), striatal medium spiny neurons (MSNs) are particularly sensitive to the presence of a CAG repeat in the huntingtin (HTT) gene." (PMID 31790427, 2019). "Following these criteria, we engineered genetic devices that recognize NS3, HTT, and Tat/Nef proteins, respectively, specific for HCV, Huntington’s disease, and HIV." (PMID 29760420, 2018). "In Huntington’s disease, SIRT1 overexpression ameliorates the neurotoxic effect of the mutant protein HTT while overexpression reverses this effect." (PMID 30504847, 2018). "Human huntingtin (Htt) contains 3144 amino acids and has an expanded polyglutamine region near the NH2-terminus in patients with Huntington’s disease." (PMID 29789657, 2018). "Caspase-6-mediated cleavage of mutant huntingtin protein and amyloid precursor protein (APP) is critical for the onset of Huntington’s disease and Alzheimer’s disease respectively." (PMID 28659495, 2017). "For example, a study on Huntington's disease (HD) showed that increasing autophagy with rapamycin could restore glutamate uptake function in primary astrocytes from rat pups expressing the mutant Huntingtin (Htt-552) protein, which is commonly found in the brains of HD patients." (PMID 28788100, 2017). "Huntington's disease (HD) is a prototypic neurodegenerative disorder, characterized by abnormally long CAG repeat expansions in the first exon of the Huntingtin gene." (PMID 27273432, 2016). "We recently developed a ZF transcription repressor (ZF-KOX1) able to bind to expanded DNA CAG-repeats in the huntingtin (HTT) gene, which are found in Huntington’s disease (HD)." (PMID 27600816, 2016). "Huntington’s disease (HD) is a fatal, dominantly inherited, neurodegenerative disorder due to a pathological expansion of the CAG repeat in the coding region of the HTT gene." (PMID 27199664, 2016). "In individuals with Huntington’s disease (HD), CAG repeats of the huntingtin gene IT15 (copy number >35–40) produce variations in the huntingtin protein, leading to duplicated glutamine residues." (PMID 26029363, 2015). "In Huntington's disease, expansion of a CAG triplet repeat occurs in exon 1 of the huntingtin gene (HTT), resulting in a protein bearing>35 polyglutamine residues whose N-terminal fragments display a high propensity to misfold and aggregate." (PMID 25464275, 2014). "Huntington disease (HD) is a devastating, incurable neurodegenerative condition, caused by CAG repeat expansion in the IT15 gene, which encodes an expanded polyglutamine tract in the target protein, huntingtin (Htt)." (PMID 23409115, 2013). "Chorea and psychiatric symptoms are hallmarks of Huntington disease (HD), a neurodegenerative disorder, genetically characterized by the presence of expanded CAG repeats (>35) in the HUNTINGTIN (HTT) gene." (PMID 24223692, 2013). "Huntington’s disease (HD) is a dominantly inherited, neurodegenerative disorder, due to a (CAG)n repeat expansion in the HTT gene." (PMID 22474619, 2012). "Expression of mutant huntingtin leads to a pronounced defect in ERAD, and UPR activation was noted in postmortem Huntington's disease brains." (PMID 21808733, 2011).
Huntington disease (continued). "Specifically protein aggregation presents one of the common features in numerous neurodegenerative disorders including the α-synuclein containing LB/LN in PD, the beta-amyloid plaques in Alzheimer's disease (AD) and the mutant huntingtin cytoplasmic inclusions in Huntington disease (HD)." (PMID 20736035, 2011). "Huntington's disease (HD) is a rare, autosomal dominant, neurodegenerative disorder resulting from expansion of a CAG repeat within the IT15 huntingtin (htt) gene on chromosome 4p." (PMID 19319184, 2009). "Huntington Disease (HD) is a late-onset, autosomal dominant neurodegenerative disorder characterized at the genetic level by expansion of a CAG repeat in the huntingtin (htt) gene." (PMID 19789644, 2009). "Antibodies 11G2 and 1B12 did not immunoprecipitate HTT1a in brain lysates from Huntington’s disease Q140 or Q111 mice whereas under the same conditions full-length WT and mutant HTT were immunoprecipitated by antibody 2B7." (PMID 40926977, 2025). "Huntington disease (HD), a genetic neurodegenerative disorder characterized by progressive motor dysfunction, cognitive impairment, and neuropsychiatric symptoms, arises from a CAG repeat expansion in the huntingtin gene (HTT)." (PMID 39946413, 2025). "1B12 and 11G2 antibodies did not immunoprecipitate huntingtin (HTT) proteins from either Huntington’s disease mouse or human brain lysates using conditions that pulled down full-length HTT with anti-HTT antibody 2B7." (PMID 40926977, 2025). "Huntington’s disease, caused by an expanded CAG trinucleotide repeat in the HTT gene encoding a non-functional huntingtin protein, is often associated with psychiatric features in addition to motor dysfunction." (PMID 40400398, 2025). "Similarly, in Huntington’s disease (HD), the HTT gene produces multiple isoforms via alternative splicing, impacting the aggregation properties of the huntingtin protein and contributing to HD pathology." (PMID 40735840, 2025). "Huntington's disease (HD) is a rare inherited disease induced by the expansion of the CAG trinucleotide repeat sequence in the huntingtin (HTT) gene, leading to misfolding of the huntingtin protein and the formation of huntingtin aggregates in cells." (PMID 41437984, 2025). "Huntingtin (HTT) function is enigmatic, as the native protein plays critical roles in neuronal health, while mutant HTT (mHTT), carrying an expanded polyglutamine stretch, triggers neurotoxicity and contributes to the pathogenesis of Huntington’s disease (HD)." (PMID 40777236, 2025). "Huntington’s disease (HD) is a progressive neurodegenerative disorder caused by a mutation in the HTT gene, leading to the production of a non-functional huntingtin protein." (PMID 41480464, 2025). "Finally, in Huntington’s disease (HD), the trinucleotide CAG expansion in the huntingtin gene (HTT) lead to the production and intracellular accumulation of abnormal huntingtin (Htt) protein with N-terminal polyglutamine repeat expansion inside neurons." (PMID 39161653, 2024). "The oligomerization state of the POI is also a consideration, and degraders have been developed for Huntington's disease that target aggregated mutant huntingtin (mHTT) but not the wild‐type HTT." (PMID 39673076, 2024). "In patients with early Huntington’s disease, intrathecal administration of HTTRx did not result in serious adverse events and led to dose-dependent reductions in mutant huntingtin levels." (PMID 39551864, 2024). "Previous studies have suggested a relationship between the number of CAG triplet repeats in the HTT gene and neurodegenerative diseases not related to Huntington's disease (HD)." (PMID 38418081, 2024). "Huntington’s disease (HD), a progressive, inherited neurodegenerative disease affecting the striatum, cerebral cortex, and thalamus, arises from an abnormal expansion of the CAG trinucleotide repeat in the huntingtin (HTT) gene." (PMID 38929088, 2024).